MYT1 (myelin transcription factor 1)
Description:
Binds to the promoter region of genes encoding proteolipid proteins of the central nervous system. May play a role in the development of neurons and oligodendroglia in the CNS. May regulate a critical transition point in oligodendrocyte lineage development by modulating oligodendrocyte progenitor proliferation relative to terminal differentiation and up-regulation of myelin gene transcription.
Synonyms: MyTI; MTF1; PLPB1; ZC2HC4A; NZF2; ZC2H2C1; C20orf36
Tractability: Small molecule: it belongs to a druggable protein family. PROTAC: ubiquitination databases record sites on it; a small molecule that binds it is known.
Target class: Transcription factor
Gene: Protein-coding gene on chromosome 20 (64,102,222 to 64,242,253, forward strand). Ensembl gene ENSG00000196132.
Subcellular location: Nucleus
Subcellular location (Human Protein Atlas): Nucleoplasm; Cytosol
Gene Ontology:
Molecular function: DNA-binding transcription factor activity; DNA-binding transcription factor activity, RNA polymerase II-specific; zinc ion binding
Biological process: regulation of DNA-templated transcription; regulation of transcription by RNA polymerase II
Cellular component: nucleoplasm; chromatin; nucleus
Genetic constraint (gnomAD): Loss-of-function variants: 23 observed, 126.56 expected, observed/expected ratio (o/e) 0.18, 90% interval 0.13 to 0.26. The upper end of that interval is the gene's LOEUF score, 0.26, which puts it in group 1 of 6, group 1 being the genes least tolerant of losing a copy. Missense variants: 1,125 observed, 1,533.9 expected, observed/expected ratio (o/e) 0.73, 90% interval 0.7 to 0.77. Synonymous variants: 518 observed, 597.96 expected, observed/expected ratio (o/e) 0.87, 90% interval 0.81 to 0.93.
Homologues: Orthologues: chimpanzee MYT1 (99% identical), macaque MYT1 (97% identical), guinea pig MYT1 (91% identical), mouse Myt1 (91% identical), rat Myt1 (91% identical), dog MYT1 (91% identical), pig MYT1 (86% identical), tropical clawed frog myt1 (70% identical), zebrafish myt1a (59% identical), zebrafish myt1b (58% identical), Caenorhabditis elegans ztf-11 (15% identical), Drosophila melanogaster Pits (7% identical), and 1 more. Paralogues in human: MYT1L (50% identical), ST18 (43% identical), IRF2BPL (11% identical), IRF2BP2 (10% identical), IRF2BP1 (9% identical).
Diseases named in the same sentence as MYT1 in open-access papers:
MYT1 is named in the same sentence as 38 diseases in open-access papers, as found by Europe PMC text mining. Sharing a sentence is not in itself a finding about the gene and the disease. The quoted sentences say what the papers report.
breast carcinoma (9 papers, 2010 to 2024). "The Myt-1 gene is associated with G2/M arrest and is repressed by miR-27a in colon and breast cancer cells." (PMID 21864401, 2011). "FKA induces G2M arrest in cell cycle progression of HER2-overexpressing breast cancer cell lines through inhibition of Cdc2 and Cdc25C phosphorylation and downregulation of expression of Myt1 and Wee1 leading to increased Cdc2 kinase activities." (PMID 28335434, 2017). "Herceptin plus FKA treatment leads to an enhanced growth inhibitory effect on HER-2 overexpressing breast cancer cell lines through downregulation of Myt1, Wee1, Skp2, survivin, and XIAP." (PMID 28335434, 2017). "In breast cancer cells miR-27a acts as an oncogene by targeting Myt-1, which blocks cell cycle progression at G2-M and through regulation of Sp proteins that have an important role in angiogenesis and growth of cancer cells." (PMID 20668671, 2010). "In addition, FKA enhanced the growth inhibitory effect of HER2 specific antibody Herceptin on HER2-overexpressing breast cancer cell line by down-regulation of Myt1, Wee1, survivin, and XIAP." (PMID 28335434, 2017). "After treatment with bakuchiol, the expression levels of P-Cdc2 (Tyr15), Myt1 and P-Wee1 (Ser642) were upregulated in breast cancer cells, thus suggesting that bakuchiol-induced Cdc2 (Tyr15) phosphorylation may play a central role in S phase arrest in bakuchiol-treated cells." (PMID 27252650, 2016). "Blocking the CXCL12/CXCR4 pathway may suppress the growth of breast cancer cells by reducing the expression of proteins that facilitate the G2-M phase transition (PLK1, Myt1, and cyclin B1), and then disrupting mitotic processes." (PMID 39703847, 2024). "The combined effect of Herceptin and FKA on downregulation of Cdc2 inhibitors (i.e., Myt1 and Wee1) and inhibitors of apoptosis (i.e., survivin and XIAP) is likely attributable to the enhanced growth inhibition of HER2-overexpressing breast cancer cells by these two agents." (PMID 28335434, 2017).
glioblastoma (8 papers, 2018 to 2025). The most malignant astrocytic tumor (WHO grade IV). "We have also found that LCS1269 triggered G2 cell cycle block associated with Wee1/Myt1 axis activation, the upregulation of transcription factor Forkhead Box M1 (FOXM1), and its target Polo Like Kinase 1 (PLK1) in human glioblastoma cell lines." (PMID 40649791, 2025). "Myt1 has been shown to limit the growth of glioblastoma in a xenograft model by regulating the expression of RNA-binding protein Rbfox1." (PMID 35409080, 2022). "Recent studies have shown that MYT1 is also involved in the malignant progression of gastric cancer, liver cancer, and glioblastomas." (PMID 35251475, 2022). "In contrast, MYT1 levels were increased in oligodendroglioma and astrocytoma more than in a normal brain, but its expression in both astrocytoma and glioblastoma was significantly lower than in oligodendroglioma." (PMID 35409080, 2022). "Interestingly, MYT1 is a transcription factor involved in neuronal differentiation, that acts as a repressor of the neural progenitor transcriptional program, which is largely shared with that working in glioblastoma initiating cells." (PMID 29643989, 2018). "MYT1 is overexpressed in IDH and RTK I glioblastoma relative to normal brain, and shows corresponding hypomethylation and active chromatin states in the gene promoter and in known enhancer regions." (PMID 33339831, 2020). "Moreover, we have previously identified LCS1269 as a potential anti-glioblastoma agent, probably interfering with cell cycle regulation through both direct CDK1 inhibition and indirect modulation of CDK1 activity through Wee1/Myt1 and FOXM1/Plk1 signaling pathways." (PMID 40649791, 2025). "It has been shown that inhibition of STAT3 in glioblastoma stem cells (GBM-SC) can promote the levels of histone H3K27 demethylation and the expression of neural-specific genes, such as FGF21, GDF15, and Myt1." (PMID 34217316, 2021).
glioma (3 papers, 2022 to 2025). A benign or malignant brain and spinal cord tumor that arises from glial cells (astrocytes, oligodendrocytes, ependymal cells). "Herein, we describe a selection of oncogenic (GLI-1/2/3, E2F1–8, STAT3, and HIF-1/2) and tumor suppressor (NFI-A/B, TBXT, MYT1, and MYT1L) TFs that are deregulated in gliomas and are subsequently associated with tumor development, progression, and migratory potential." (PMID 35409080, 2022). "In contrast, key regulators of OPC specification and maintenance, including MYT1, OLIG2, PDGFRA, PTPRZ1, SMOC1, and SOX8 were hypomethylated in PM gliomas." (PMID 37055795, 2023). "The benefits of JLK1486-treatment derive from its ability to activate various transcription factors, such as Myt1, STAT1, and peroxisome proliferator-activated receptor γ, in glioma cells." (PMID 35409080, 2022).
Anxiety (2 papers, 2022). Intense feelings of nervousness, tension, or panic often arise in response to interpersonal stresses. "The overexpression of MYT1 was suggested to help reduce anxiety in rats and has been associated with intellectual disability previously." (PMID 35391799, 2022). "In rats, the overexpression of the myelin transcription factor 1 (MyT1) promotes differentiation of oligodendrocytes, which is also regulated by Plp1 and Mbp, and ameliorates anxiety-like and compulsive behaviors." (PMID 35326487, 2022).
bladder cancer (2 papers, 2015 to 2022).
Diabetes (2 papers, 2024 to 2026). "Fourth, the Neurog3+ progenitors that are exposed to maternal overnutrition, an established risk factor for diabetes, express lower levels of DNMT3a and Myt1." (PMID 38496675, 2024). "Thus, although Myt1 co-expression with Neurog3 during embryogenesis represents the progenitors of better-function cells, this model is not fit for studying b-cell subtype stability in diabetes-prone models at postnatal stages." (PMID 38496675, 2024).
hepatocellular carcinoma (2 papers, 2018 to 2022). A malignant tumor that arises from hepatocytes. "In hepatoma cells, the target gene PLK1 of lncRNAP26302 was overexpressed, inhibiting the expression of Myt1 and reducing the inhibitory effect of Myt1 on CycA/CDK1." (PMID 30364632, 2018).
astrocytoma (1 paper, 2022). "They further examined the relative expression levels of MYT1 and MYT1L in human brain cancer datasets showing that MYT1L was expressed in a lower rate in oligodendroglioma, astrocytoma (grade III), and GBM compared to normal brains." (PMID 35409080, 2022).
autism spectrum disorder (1 paper, 2024). A spectrum of developmental disorders that includes autism, and Asperger syndrome. "MYT1 is a drug target for autism spectrum disorder and is less characterised, it binds to the promoter regions of proteolipid proteins of the central nervous system and plays a role in the developing nervous system." (PMID 38969939, 2024).
colon cancer (1 paper, 2015). "Chintharlapalli and colleagues demonstrated, for the first time, that CDODA-Me, a synthetic derivative of glycyrrhetinic acid, acts by downregulating miR-27a that is accompanied by an enhanced expression of ZBTB10 and Myt-1 which produces cell cycle arrest in colon cancer cells." (PMID 25915942, 2015).
congenital adrenal hyperplasia (1 paper, 2022). Congenital adrenal hyperplasia (CAH) is an inherited endocrine disorder caused by a steroidogenic enzyme deficiency that is characterized by adrenal insufficiency and variable degrees of hyper or hypo androgyny manifestations, depending of the type and the severity of the disease. "Upregulation of genes associated with other diseases, renal dysfunction or cancer was also observed, such as Fras1 (Fraser syndrome 1), Cyp21a1 (congenital adrenal hyperplasia), Dbh (associated with kidney dysfunction), and Akr1c1/Myt1/Myf6/Scg2 (kidney cancer)." (PMID 36130284, 2022).
Dias-Logan syndrome (1 paper, 2021). Any BAFopathy in which the cause of the disease is a mutation in the BCL11A gene.
Infertility (1 paper, 2022). "The mechanism by which the suppression of wee-1.3 (RNAi) infertility occurs is still unknown but future studies may offer new insights into the regulation of this highly conserved WEE-1.3/Myt1 cell cycle kinase." (PMID 36060813, 2022).
malaria (1 paper, 2011). Malaria is a serious and sometimes fatal disease caused by a parasite that commonly infects a certain type of mosquito which feeds on humans. "Interestingly, in malaria parasites there are no candidates for Polo-like kinases, neither are there strong candidates for the network of proteins regulating the activation of the cyclin B–Cdk1 complex such as the mitotic cyclin-CDK inhibitory kinases Wee1 and Myt1 and the Cdc25 phosphatase." (PMID 21166904, 2011).
neuroblastoma (1 paper, 2021). Neuroblastoma (NB) is the most common solid, extracranial childhood tumor. "A key feature of neuroblastoma is the impaired neuronal differentiation in parallel to the high expression of myelin transcription factor 1 (MYT1)." (PMID 34082769, 2021). "Knockdown of MYT1 induced neuro-differentiation in neuroblastoma cells." (PMID 34082769, 2021).
osteosarcoma (1 paper, 2022). A usually aggressive malignant bone-forming mesenchymal neoplasm, predominantly affecting adolescents and young adults. "Therefore, MYT1 depletion in osteosarcoma may contribute to the increased cell proliferation in the presence of chromosomal aberrations." (PMID 35887382, 2022).
ovarian carcinoma (1 paper, 2013). A malignant neoplasm originating from the surface ovarian epithelium. "Furthermore, analyses of cell cycle-related proteins suggest that Corilagin arrested ovarian cancer cells in the G2/M phase by down-regulating the expression levels of Cyclin B1, Myt1, Phospho-Weel (p-Weel) and Phospho-cdc2 (p-cdc2)." (PMID 23410205, 2013). "We also observed down-regulation of p-Wee1 (Ser642) and Myt1 in Hey and SKOv3ip cells, indicating that the efficacy of Corilagin in inducing G2/M arrest in ovarian cancer cells is possibly due to the down-regulation of cdc2 and Cyclin B1 through Wee1 and Myt1 regulation." (PMID 23410205, 2013).
prostate carcinoma (1 paper, 2023). A carcinoma that arises from epithelial cells of the prostate gland. "Overexpression of NK1R in epithelial prostate cancer cells was able to induce a shift of lineage plasticity, leading to the reduction of AR and PSA levels, the gain of the expression of CgA, ENO2, AURKA, N-Myc, MYT1, and SRRM4." (PMID 37385990, 2023).
restless legs syndrome (1 paper, 2017). A condition that occurs while resting or lying in bed; it is characterized by an irresistible urgency to move the legs to obtain relief from a strange and uncomfortable sensation in the legs. "The BI-ENRICH algorithm showed that most of the top pathways identified for restless legs syndrome were related to neurodevelopment, including neurogenesis (genes MDGA1, MYT1, NTNG1, and SEMA6D), cell-junction organisation (PKP4 and SMAD3), and axon guidance (NTNG1 and SEMA6D)." (PMID 29029846, 2017).
cancer (10 papers, 2010 to 2023). A tumor composed of atypical neoplastic, often pleomorphic cells that invade other tissues. "There are evidences from several cytology experiments showing that MYT1 is associated with carcinoma." (PMID 24015200, 2013). "Our data supports that Myt1 overexpression is a common mechanism by which cancer cells can acquire resistance to a variety of drugs entering the clinic that aim to induce mitotic catastrophe by abrogating the G2/M checkpoint." (PMID 38020882, 2023). "Since upregulation of Myt1 is a barrier towards cancer cell killing by G2/M checkpoint inhibitors, Myt1 inhibition is a potential step to subvert the resistance to Wee1 inhibition." (PMID 38020882, 2023). "In other words, during prolonged inhibition of ATR or Chk1 (such as during clinical treatment) Myt1 levels can determine the drug sensitivity of cancer cells and, as a consequence, the efficacy in cancer therapy." (PMID 38020882, 2023). "Cancer cells with intrinsic adavosertib resistance were shown to have higher levels of MYT1 than sensitive cells." (PMID 33281882, 2020). "To confirm that treatment with BI 2536 and BI 6727 inhibits activation of Plk1 in MKN45 CSC-like cells and cancer cells, we measured the phosphorylation of Myelin transcription factor 1 (Myt1), a Plk1 substrate." (PMID 28430578, 2017). "Cdk1 activity is inhibited by phosphorylation induced by Myelin transcription factor 1 (MYT1) and by the reduced expression of Cdk1 phosphatase called cell division cycle 25C (cdc25), which is highly expressed in cancer and is associated with tumor development." (PMID 37838167, 2023). "Although MYT1L itself has not previously been reported to associated with carcinoma, it is highly homologous to MYT1 and the loss of MYT1 function may be compensated by MYT1L activity." (PMID 24015200, 2013). "The importance of MYT1 has not yet been fully understood, especially in cancer cells." (PMID 30068368, 2018).
tumor (10 papers, 2013 to 2025). "Of note, the anti-tumor activity of Wee1 inhibition can be counteracted by tumor overexpression of Myt1, a kinase that also regulates the G2/M checkpoint and has somewhat overlapping activity with Wee1." (PMID 38730598, 2024). "The remaining tumor-specific L1 insertion occurred in donor 47 and was associated with activation of the transcriptional repressor suppression of tumorigenicity 18 (ST18), a member of the MYT1 zinc-finger transcription factor family." (PMID 23540693, 2013). "Importantly, Myt1 depletion cooperated with EGFR in tumor formation." (PMID 31331981, 2019). "Meanwhile, ZNF300 might activate CDK1 through inhibition of WEE1 and MYT1 and modulation of the MYC/AURKA/BORA/PLK1 axis to promote the tumour cells to overcome G2 arrest and enter the M phase to avoid the apoptosis induced by chemotherapeutic drugs." (PMID 33078469, 2020).
infection (2 papers, 2013 to 2018). The state of being infected such as from the introduction of a foreign agent such as serum, vaccine, antigenic substance or organism. "The levels of these histone modifications on the cellular promoters (ACT and MYT1) remained similar in the course of de novo infection, suggesting that the histone modification changes specifically occur on the viral genome." (PMID 24367262, 2013).
neurological disease (2 papers, 2010 to 2024). "Of those described, impaired psychomotor and behavioral development have been observed; paired with data on the gene's function, MYT1 is a good candidate gene for further study to elucidate its involvement in brain function and any associated neurological disorders influencing cognitive development." (PMID 20805988, 2010).
MYT1 also shares sentences with these, for which no sentence is quoted: adenocarcinoma (1 paper); adenoma (1); Alzheimer disease (1); cardiovascular disease (1); childhood onset schizophrenia (1); epidermoid carcinoma (1); gastric cancer (1); Intellectual disability (1); kidney cancer (1); liver cancer (1); melanoma (1); Obesity (1); oligodendroglioma (1); schizophrenia (1); type 2 diabetes (1).